TRPM2 (transient receptor potential cation channel subfamily M member 2)
Diseases named in the same sentence as TRPM2 in open-access papers (continued):
Sharing a sentence is not in itself a finding about the gene and the disease.
neck cancers (1 paper, 2019). "It has been reported that TRPM2 is expressed in many cancer types such as bladder, breast, lung, liver, head, and neck cancers." (PMID 30997980, 2019).
nephrotoxicity (1 paper, 2025). Toxicity that causes injury to the kidney or damages its function. "This study investigated the protective effect of selenium (Se) in a cadmium (Cd)-induced nephrotoxicity model in rats and the role of the TRPM2 channel in this mechanism." (PMID 39997902, 2025).
oral cancer (1 paper, 2019). "Our observation of significant epigenetic upregulation of TRPM2 and LCK is consistent with earlier reports on oral cancer and oral lichen planus (oral pre-cancer)." (PMID 31796082, 2019).
pancreatitis (1 paper, 2020). Inflammation of the pancreas. "In addition, genetic deletion of TRPM2 reduced the severity of bile-acid-induced experimental pancreatitis; however, we did not observe this protective effect in cerulein-induced AP in TRPM2 knockout mice." (PMID 32503336, 2020).
papilloma (1 paper, 2016). A benign epithelial neoplasm that projects above the surrounding epithelial surface and consists of villous or arborescent outgrowths of fibrovascular stroma. "The aim of this study is to assess the expression of TRPM2 channels in human HSCC compared with adjacent normal tissue and papilloma tissue, as well as its functional expression in the highly HSCC cancer cell lines (SCC-9)." (PMID 28008929, 2016). "No obvious staining of TRPM2 was observed in normal tongue tissues (Control, n = 9), while weakly positive TRPM2 staining was observed in 6/12 papilloma of tongue specimens (PA) and negative TRPM2 staining was observed in the rest of papilloma specimens." (PMID 28008929, 2016).
peritonitis (1 paper, 2021). Inflammation of the peritoneum (tissue that lines the abdominal wall and covers most of the organs in the abdomen). "TRPM2 is highly expressed on myeloid cells, and the adverse effect of oxidative stress during inflammation as seen in peritonitis may be due to over-activation of TRPM2." (PMID 34135384, 2021).
pneumonia (1 paper, 2014). An acute, acute and chronic, or chronic inflammation focally or diffusely affecting the lung parenchyma, caused by an infection in one or both of the lungs (by bacteria, viruses, fungi, or mycoplasma.). "If the TRPM2 allele implicated in our study were associated with increased TRPM2 expression, it might consequently be associated with greater likelihood of pneumonia development as a result of greater neutrophil invasion." (PMID 24892408, 2014).
post-traumatic stress disorder (1 paper, 2025). An anxiety disorder precipitated by an experience of intense fear or horror while exposed to a traumatic (especially life-threatening) event. "Our results indicate that TRPM2 plays a positive role in retention of contextual fear memory by modulating neuronal activity in the hippocampus, and suggest that TRPM2 activity could potentially be targeted to strengthen extinction-based exposure therapies for post-traumatic stress disorder (PTSD)." (PMID 40016847, 2025).
Pruritus (1 paper, 2023). Pruritus is an itch or a sensation that makes a person want to scratch. "Considering that MRGPRs serve as G-protein-coupled metabotropic receptors for bilirubin, our current work raises the possibility that bilirubin may also act on TRPM2 channels, which are known to be expressed in DRG neurons, contributing to the phenomenon of pruritus." (PMID 36921602, 2023).
pulmonary fibrosis (1 paper, 2015). Chronic progressive interstitial lung disorder characterized by the replacement of the lung tissue by connective tissue, leading to progressive dyspnea, respiratory failure, or right heart failure. "Collectively, it appears that dust particles-mediated TRPM2 activation facilitates inflammatory events in COPD and pulmonary fibrosis patients." (PMID 26640326, 2015).
pulpitis (1 paper, 2019). Inflammation of the dental pulp. "TRPM2 expression is also increased in the pulpal fibroblasts of teeth with signs of irreversible pulpitis." (PMID 30691193, 2019). "TRPM2 has also been detected in the fibroblasts of human dental pulp, and its expression is upregulated in teeth with signs of irreversible pulpitis." (PMID 30691193, 2019).
radiodermatitis (1 paper, 2019). A cutaneous inflammatory reaction occurring as a result of exposure to biologically effective levels of ionizing radiation. "In the present study, we have evaluated the contribution of TRPM2 to radiodermatitis, including irradiated skin damage, lesions and weight loss, and have attributed these responses to increased production of inflammatory mediators." (PMID 30483886, 2019). "Our results emphasize the importance of TRPM2 in mediating radiation-induced inflammatory responses and suggest TRPM2 as a potential target when considering therapeutic interventions for radiodermatitis." (PMID 30483886, 2019). "To test whether local administration of TRPM2 inhibitors is sufficient to protect against radiodermatitis, we administered a topical TRPM2 inhibitor (clotrimazole) following irradiation of WT mice." (PMID 30483886, 2019). "Thus, inhibiting TRPM2 may reduce the severity of radiodermatitis by dampening inflammation systematically and thus halting the vicious cycle of chronic immune activation and tissue injury." (PMID 30483886, 2019). "Clotrimazole did not improve the outcome of radiation-induced dermatitis, thus confirming the importance of TRPM2-induced immune activation." (PMID 30483886, 2019).
Sjögren’s Syndrome (1 paper, 2018). "These interesting findings point to the possible involvement of TRPM2 in Sjögren’s Syndrome, although further studies will be required to identify the exact role of TRPM2 in this disease." (PMID 29997338, 2018). "Based on currently available data highlighting the role of TRPM2 in inflammatory process, it will be very important to assess whether TRPM2 contributes to Sjøgren’s Syndrome (SS)." (PMID 29997338, 2018). "However, currently, direct evidence for TRPM2 involvement in Sjøgren’s Syndrome (SS) is lacking." (PMID 29997338, 2018).
stress-related disorder (1 paper, 2025). Stress-related disorders are mental health disorders that are a result of an atypical response to both short and long-term anxiety due to physical, mental, or emotional stress. "It will also be important to investigate the long-lasting effects of TRPM2 inhibition and whether these effects can be harnessed for clinical therapies aimed at treating trauma- and stress-related disorders." (PMID 40016847, 2025).
tongue SCC (1 paper, 2020). "TRPM2 protein expression is significantly increased in tongue SCC compared to non-malignant tongue tissues (control or papilloma)." (PMID 32182937, 2020). "In two human tongue SCC cell lines, TRPM2 expression was upregulated compared to a non-tumorigenic oral epithelial cell line." (PMID 32182937, 2020).
tongue tumor (1 paper, 2016). "In tongue tumor tissues, the mRNA levels of TRPM2 were significantly increased compared with those in the control or PA group." (PMID 28008929, 2016). "Consistent with the data from human tongue tumor samples, the positive staining of TRPM2 was observed in SCC-9 and SCC-25 cells." (PMID 28008929, 2016).
vascular dementia (1 paper, 2021). A degenerative vascular disorder affecting the brain. "Next, we plan to further elucidate the molecular mechanism of PAE in improving vascular dementia rats from the relationship between NMDAR/TRPM2 signaling pathway and pro-inflammatory response of microglia." (PMID 34903262, 2021).
tumor (79 papers, 2014 to 2025). "Overall, we observed that TRPM2 expression was strongly associated with the survival outcomes of patients with multiple tumor types." (PMID 37569287, 2023). "TRPM2 was shown to facilitate tumor cell proliferation but also contribute to tumor susceptibility to neutrophil cytotoxicity." (PMID 37649595, 2023). "TRPM2 expression is increased in cancerous tissues, making tumor cells more susceptible to neutrophil cytotoxicity." (PMID 35784290, 2022). "We found that TRP family genes are extensively involved in tumour progression and serve as risk factors for most tumours— especially TRPM2, TRPM4, and TRPM8 leading to poor prognosis of patients with cancer." (PMID 35493463, 2022). "Studies have shown that TRPM2 expression is elevated in circulating tumor cells (CTC) compared with the primary tumor, rendering CTC more susceptible to neutrophil cytotoxicity." (PMID 35784290, 2022). "In pancreatic cancer, high TRPM2 expression was associated with tumor proliferation, invasive ability, and poor prognosis, although the mechanism was not defined." (PMID 36446940, 2022). "Our results showed that all of TRPM2-deficient A549 tumor cells exhibited a significant reduction of tumor burden compared with that of control but independent on the expression of CD38." (PMID 34226519, 2021). "In OrSCC, low TRPM2-expression was associated with poorly- or moderately-differentiated, tumor tissue grades." (PMID 36046118, 2021). "The association plots derived from the 533 KIRC cases in TCGA showed that the upregulation of TRPM2 expression was significantly associated with shorter OS, poor pathological stage, and tumor grade in KIRC (respectively)." (PMID 35071322, 2021). "All data indicated that TRPM2 was activated by oxidative stress, leading to activation of caspases-3 and -9 and changing of the expression of the related tumor-associated factors, and finally promoting the apoptosis in cultured SCC9 cells." (PMID 28008929, 2016). "The infiltrating of tumor-associated macrophages (TAMs), Tex, Tc, Type 1 T helper (Th1) and immunoregulatory Treg (iTreg) abundances showed a significant positive correlation with TRPM2 expression." (PMID 37569287, 2023). "Overexpression of TRPM2 increases tumor susceptibility to oxidative stress, favoring the mitochondrial Ca2+ overload and triggering the intrinsic pathway of apoptosis, so TRPM2 is considered as a tumor suppressing factor." (PMID 25866806, 2015). "Moreover, we evaluated the association between TRPM2 expression and immune-related biomarkers such as immune cell infiltration and checkpoint-related genes to further explore the relevance of its expression to tumor immunity." (PMID 37569287, 2023). "Inhibition of the TRPM2-mediated calcium influx is associated with increased ROS production, impairments in autophagy and DNA repair, defective mitochondrial metabolism, reduced cellular bioenergetics, decreased tumor growth and increased sensitivity to chemotherapy." (PMID 33856653, 2021). "Unlike other TRP channels that directly stimulate proliferation or migration, TRPM2 appears to support tumor cell viability by regulating mitochondrial function, redox homeostasis, and DNA damage responses." (PMID 40869148, 2025). "The third article, “TRPM2 Mediates Neutrophil Killing of Disseminated Tumor Cells,” identifies the mechanism by which neutrophils kill disseminated tumor cells in a Ca2+-dependent manner via TRPM2, shedding light on how neutrophils limit metastatic spread." (PMID 40160822, 2025). "Beyond its role in tumor adaptation, TRPM2 presents as an actionable target due to its selective activation under oxidative conditions." (PMID 40869148, 2025). "Another interesting study have shown that neutrophil-produced H2O2 activates transient receptor potential cation channels (TRPM2), resulting in the uptake of lethal levels of calcium ions by tumor cells." (PMID 40160822, 2025).
tumor (continued). "TRPM2 activation has been shown to support tumor growth by maintaining mitochondrial integrity and suppressing ROS accumulation." (PMID 41306344, 2025). "Further, the cytotoxic effect of neutrophils mediated by reactive oxygen species (ROS) has been found to rely on the expression of transient receptor potential melastatin 2 (TRPM2) on the tumor surface." (PMID 40282474, 2025). "ZGE effectively counteracted these effects, downregulating TRPM2 and restoring calcium balance, thereby sensitizing tumor cells to DOX‐induced oxidative stress and apoptosis." (PMID 41306344, 2025). "On one hand, ROS can directly kill tumor cells through oxidative bursts and induce apoptosis via TRPM2-mediated calcium influx; on the other, excessive ROS in the TME suppress T cell proliferation and enhance T cell apoptosis." (PMID 40805288, 2025). "ZGE suppresses TRPM2‐mediated calcium signaling and promotes ROS‐induced apoptosis, contributing to tumor inhibition." (PMID 41306344, 2025). "Particularly, hydrogen peroxide (H2O2) secreted by TANs induces tumor apoptosis by triggering Ca2+ influx via the TRPM2 channel (transient receptor potential cation channel, subfamily M, member 2)." (PMID 40805288, 2025). "Neutrophils secrete hydrogen peroxide (H2O2), which induces apoptosis in tumor cells through the influx of calcium ions (Ca2+) mediated by the transient receptor potential cation channel, subfamily M, member 2 (TRPM2)." (PMID 38760815, 2024). "TRPM2 supports tumor cell survival by enhancing mitochondrial function, increasing ATP production, promoting autophagy, reducing ROS levels, and boosting antioxidant capacity." (PMID 39007141, 2024). "Studies using multiple tumor cell models have shown that inhibiting TRPM2 increases cell death and sensitivity to doxorubicin." (PMID 39007141, 2024). "Adenosine diphosphate ribose (ADPR) interacts with NUDT9 homology to activate transient receptor potential melastatin 2 (TRPM2) channel, while the decreased level of TRPM2 was considered to enhance tumor potential metastasis." (PMID 38596213, 2024). "Building upon these findings, they demonstrated that H2O2 induces a lethal influx of Ca2+ in tumor cells, facilitated by the transient receptor potential cation channel, subfamily M, member 2 (TRPM2)." (PMID 38062888, 2023). "Further, these consequences were established in vivo through a SCID mouse model, and the decline of TRPM2 was directed to a decreased growth of tumor." (PMID 37337283, 2023). "The exact role of Transient receptor potential melastatin 2 (TRPM2) in tumor progression and immunomodulation remains elusive." (PMID 37569287, 2023). "First, we divided all available tumor data from KIRC into two subgroups based on the median TRPM2 expression level." (PMID 36619219, 2023). "Overall, TRPM2 has relevance to an immunosuppressive tumor microenvironment by modulating macrophage." (PMID 37569287, 2023). "The results from ImmuCellAI revealed a positive connection between TRPM2 expression and infiltration score in most tumor types, excluding COAD, DLBC, ESCA, and READ." (PMID 37569287, 2023). "To further evaluate the relationship between TRPM2 and tumor immunity, we analyzed the correlation between TRPM2 expression and immune cell markers based on TCGA-OV dataset." (PMID 37608401, 2023). "Previous reports have proved that TRPM2 promoted tumor progression via multiple mechanisms, such as drug resistance, autophagy, and immunosuppression." (PMID 37608401, 2023). "The expression of TRPM2 was significantly correlated with tumor microenvironment scores, tumor-stemness index, macrophages infiltration, immune checkpoints, and immune-related genes." (PMID 37569287, 2023). "Gene Set Enrichment Analysis (GSEA) results based on the Reactome database were in accordance with the results of GO and KEGG, indicating that, represented by OV, the TRPM2 was significantly related to various immune-related and tumor-related pathways." (PMID 37569287, 2023).
tumor (continued). "We investigated the expression profile of TRPMs in the KIRC module of the TCGA database, and the heatmap indicated that among TRPM1-8, TRPM2 was significantly upregulated in the tumor samples." (PMID 36619219, 2023). "The correlation between TRPM2 and immune-related genes, including chemokine and their receptors, and immunoregulatory genes, similarly demonstrated its intimate interactions with tumor immunity." (PMID 37569287, 2023). "On the other hand, acting through similar mechanisms, TRPM2 is an important player for reducing tumour growth and the survival of cancer cells, also protecting cells from the toxicity of some anticancer drugs (i.e. doxorubicin)." (PMID 37337283, 2023). "We also investigated the potential role of TRPM2 in immune cell infiltration in the tumor microenvironment." (PMID 36619219, 2023). "To explore the possible link between TRPM2 and tumor microenvironment, we calculated the TME-related indexes and tumor purity using the ESTIMATE R package." (PMID 37569287, 2023). "In summary, our study demonstrated that TRPM2 is highly expressed in ccRCC and facilitates tumor growth by inhibiting ER stress and enhancing EMT." (PMID 36619219, 2023). "H2O2 inhibits tumor cell growth and metastasis by inducing excess calcium influx in tumor cells through TRPM2 channels." (PMID 37563639, 2023). "In this context, Miller’s group was the first to report a key role of TRPM2 in the link between autophagy and tumor growth." (PMID 37576339, 2023). "In contrast, in a small number of malignancies, the activation of TRPM2 reduces tumor cell survival." (PMID 37569287, 2023). "Subsequently, the TCGA database was used to analyze the relationship between TRPM2 RNA expression and tumor clinical stage." (PMID 37569287, 2023). "Further, we evaluated the correlation between TRPM2 and tumor-infiltrating immune cells including B cell, CD4+ T cell, CD8+ T cell, macrophage, neutrophil, and myeloid dendritic cells." (PMID 37608401, 2023). "Activation of TRPM2 results in the expression of transcription factors and kinases that are critical for tumor cell proliferation and survival, such as CREB, HIF-1/2α, Nrf2, and Src phosphorylation." (PMID 37762313, 2023). "Our analysis revealed that TRPM2 was closely correlated with stromal score and was positively related to cancer cell stemness index in 16 tumor types." (PMID 37569287, 2023). "The expression of TRPM2 was higher in the tumor tissues than in normal tissues, and a similar result was observed in 72 paired tumor and corresponding normal tissues." (PMID 36619219, 2023). "We also conducted wound healing assays to confirm the effect of TRPM2 silencing on the migration and invasion ability of tumor cells." (PMID 36619219, 2023). "Recent studies have also shown that TRPM2 preserves cell viability in the case of other non-tumor cells, protecting them from ischemia–reperfusion injury." (PMID 37337283, 2023). "In a mice model, the TRPM2 knockdown eradicated AGS’s tumor proliferation capacity, and produced deregulation of metastatic markers." (PMID 36844925, 2022). "The inhibition of early autophagy induction was also observed, managing cell death in TRPM2-expressing tumor cells." (PMID 36844925, 2022). "Downregulation of TRPM2 also sensitized these tumor cells to chemotherapeutic agents, like doxorubicin and paclitaxel." (PMID 36844925, 2022). "TRPM2 is a potential therapeutic target to reduce tumor proliferation and increase doxorubicin sensitivity through modulation of FOXM1, E2F1, and cell cycle/DNA repair proteins." (PMID 35428820, 2022). "Using a breast cancer model, it has been shown that reduced expression of TRPM2 in tumor cells allowed neutrophil immune evasion but also led to tumor growth retardation, albeit accompanied by an increase in metastatic potential." (PMID 35784290, 2022).